INS (insulin)
Diseases named in the same sentence as INS in open-access papers (continued):
Sharing a sentence is not in itself a finding about the gene and the disease.
Hypoglycemia (continued). "Frequent nocturnal hypoglycemia may occur due to 1) the autonomic response to hypoglycemia that becomes attenuated during sleep and 2) the decreased response of counter-regulatory hormones to insulin during sleep." (PMID 26625003, 2015). "However, increasing the insulin dose may lead to adverse events such as weight gain and hypoglycemia." (PMID 26124906, 2015). "Nevertheless, people with severe renal disease (eGFRs <30 mL/min/1.73 m2) may have reduced glycogen stores and a reduced supply of gluconeogenic substrates, resulting in diminished capacity of the liver and kidney to release glucose and reverse insulin-mediated hypoglycemia." (PMID 26239457, 2015). "Against this background, the high rates of hypoglycaemia observed in patients treated with insulin in comparison to those administered incretin-based therapies in the DiaRegis study are noteworthy, with an OR of 11.45 for symptomatic hypoglycaemia and 8.33 for asymptomatic hypoglycaemia." (PMID 25645672, 2015). "Interestingly, there was no indication of higher hypoglycemia risk in combination-treated animals compared with corresponding insulin alone group." (PMID 25799496, 2015). "Thus, our results suggest that reducing the insulin dose by up to 20% and discontinuing insulin secretagogues may prevent hypoglycemia when a DPP-4 inhibitor is added to insulin therapy." (PMID 25816296, 2015). "As examples MET+ SU+ GLP-1-RA or MET+ SU+ SGLT2-i may be a good choice for patients that require weight loss and MET+ SU+ GLP-1-RA for patients at risk for hypoglycaemia, whereas MET+ SU+ insulin may provide good blood glucose control in patients where hypoglycaemia and weight gain is not a concern." (PMID 26664803, 2015). "The diabetic animals treated by insulin had their PGLs gradually restored to the normal range, indicating continuous regulation of plasma glucose levels in this study, which would avoid the major side effect of hypoglycemia usually seen in an intensive insulin therapy." (PMID 26783411, 2015). "The capsulated insulin administered by oral gavage lowered fasting blood glucose levels by up to 50% in a sustained and dose-dependent manner and reduced postprandial glycemia in streptozotocin-induced diabetic mice without causing hypoglycemia." (PMID 24833901, 2014). "The episodes of hypoglycemia during childhood in the human patients, associated with the lack of a blockade of insulin release, may be accounted by a decrease in the inhibition of basal insulin release by Rbcn-3α." (PMID 25248098, 2014). "However, diabetic patients may also experience hypoglycemia, as a result of inappropriate doses of insulin." (PMID 24616659, 2014). "Indeed, the addition of sitagliptin to insulin therapy provided significant improvement in glycaemic control without increased risk of hypoglycaemia and clinically-relevant weight gain." (PMID 24607023, 2014). "This work aimed at investigating whether liver glucose release and its stimulation by adrenaline and glucagon could explain the change in the profile of the insulin-induced hypoglycaemia observed in vivo in food-restricted rats subjected to an acute exercise session." (PMID 24719616, 2014). "While it remains ill-defined whether low glucose directly stimulates glucagon release during hypoglycemia, the paracrine/endocrine (interstitium/microcirculation) inhibitory effects of insulin and somastostatin on glucagon secretion are relatively well established." (PMID 25177371, 2014). "XMetS improved the response to exogenous insulin without causing hypoglycemia." (PMID 24533136, 2014). "However, one major feared side effect of insulin therapy is iatrogenic hypoglycemia, which might occur in almost 90% of all insulin treated patients." (PMID 24574966, 2014). "However, increased risk of hypoglycemia, weight gain and non-physiological insulin delivery (i.e., systemic vs. portal), in addition to fear of injections, limit its use." (PMID 26237486, 2014).
Hypoglycemia (continued). "Consequently, high IGF-1 serum levels would be associated with hypoglycemia before and after bariatric surgery independent of insulin secretion." (PMID 24736741, 2014). "This might be due to a lack of knowledge among non-insulin using participants regarding the potential risk of hypoglycaemia caused by insulin use, though almost half of this sample agreed or strongly agreed that this was a risk." (PMID 24902877, 2014). "In conclusion, we show that alprazolam reduces some neuroendocrine and sympathetic nervous system responses to insulin-induced hypoglycemia and, furthermore, that this model may be valuable for further assessing the role of GABAergic pathways in the pituitary and adrenal medulla." (PMID 24770625, 2014). "Furthermore, the VISEP study, which found that intensive insulin therapy did not reduce mortality in septic patients, was discontinued early due to an excess risk for hypoglycemia." (PMID 25136614, 2014). "Considering the increased risk of death due to increased hypoglycemia and the findings that intensive insulin therapy does not reduce mortality, the use of IIT as a strategy to maintain normoglycemia remains unclear." (PMID 25136614, 2014). "However, more recent evidence suggests that appropriate training in insulin adjustment can improve HbA1c without significantly increasing the risk of severe hypoglycaemia." (PMID 24511312, 2014). "Thus, therapeutically increasing insulin doses may result in increased peripheral hyperinsulinemia in patients with DM-NAFLD, further increasing the risk of hypoglycemia." (PMID 24397589, 2014). "Moreover, lower insulin use could reduce side effects of insulin treatment such as hypoglycemia and weight gain." (PMID 25175981, 2014). "Hypoglycaemia in insulin-treated patients may occur because of the release of the hormone from the circulating insulin–antibody complex, but in general, these antibodies rarely affect the course of the disease, the daily insulin requirements or the glycaemic control." (PMID 24711924, 2014). "In that study, the mean period of hypoglycemia after liraglutide administration was approximately 50 min/day and a higher frequency of hypoglycemia was observed after liraglutide injection than after administration of insulin or DPP-4 inhibitors such as vildagliptin and alogliptin." (PMID 25526642, 2014). "Therefore, there is a need for new insulin-independent antidiabetic drugs that have a low risk of hypoglycemia, do not increase body weight, and improve the clinical features of diabetes mellitus." (PMID 24678906, 2014). "With recent improvements in insulin therapy, it is not clear whether the inverse association between the incidence of severe hypoglycemia and HbA1c levels still exists." (PMID 25289645, 2014). "The liver was a primary site for insulin clearance via first-pass transit, and thus, reduction of liver mass in combination with reduced liver cell stores of glycogen and gluconeogenesis in chronic liver diseases raised concern for the development of hypoglycemia." (PMID 25295519, 2014). "As well as self-management requires that parents know how to prepare and give insulin injections, monitor blood glucose and urine kitones, record blood level values, manage diet including developing meal plans, manage exercise, and manage acute problems particularly hypoglycemia." (PMID 24171891, 2013). "Indeed, we found that oral administration of Diapin significantly reduced the casual blood glucose levels in diabetic mice without causing hypoglycemia even under non-insulin resistance states, suggesting that Diapin therapy has little risk of hypoglycemia." (PMID 24386218, 2013). "The glucose-dependent action of fasiglifam makes it a promising candidate for a novel therapy for diabetes with a low risk of hypoglycemia, in contrast to the widely prescribed antidiabetic drug sulfonylurea, which increases insulin release regardless of glucose levels and can lead to hypoglycemia." (PMID 24130766, 2013).
Hypoglycemia (continued). "Therefore, it was not possible to analysis the potential associations between insulin injection frequency (particularly injections at night),usage of OADs,or nocturnal hypoglycaemia with sleep quality." (PMID 23383010, 2013). "The use of proinsulin cDNA rather than mature, processed insulin is also advantageous because serum proinsulin has a longer half-life, yet roughly 25% of the efficacy of mature human insulin, which may reduce the potential for hypoglycemia in the event of chronic overexpression." (PMID 23554999, 2013). "Insulin was usually, but not always, associated with more hypoglycemia than exenatide." (PMID 23256660, 2013). "Thus, concomitant VMH NO and ROS production during insulin-induced hypoglycemia may increase S-nitrosylation levels." (PMID 23894333, 2013). "However, intensive insulin therapy is limited by the induction of iatrogenic hypoglycemia." (PMID 23894333, 2013). "Both hypoglycemic episodes were classified as “asymptomatic" and were not related to established major risk factors of ICU hypoglycemia such as nutritional interruption, asynchrony of nutrition and insulin administration, delayed glucose measurement, or drug administration." (PMID 23555075, 2013). "The expected hypoglycemia after intraperitoneal injection was significantly inhibited in the CH Group compared to the C Group (the glycemic decay in response to intraperitoneal ITT in the ChM Group was significantly recovered after CM treatment as an index of the peripheral insulin sensitivity)." (PMID 24119413, 2013). "Moreover, aliskiren increased systemic insulin sensitivity with hypoglycemia in the MCD mice." (PMID 24204981, 2013). "For example, hypoglycaemia is known to be a regular event for insulin-requiring diabetic patients; however, if hypoglycaemia is strongly linked to CV risk, then it remains unclear why many patients do not show CV problems after repeated exposure to hypoglycaemic episodes." (PMID 24053606, 2013). "Though insulin is a lifesaving therapy, it does not ameliorate the underlying autoimmune process, and exogenous insulin use has major drawbacks including weight gain and risk of hypoglycemia." (PMID 24223938, 2013). "Thus, insulin injection used in our clinically relevant model of hypoglycemia may also contribute to the increased VMH ROS production." (PMID 23894333, 2013). "In addition, frequent hypoglycemia attacks in patients treated with oral hypoglycemic drugs or insulin injection can produce RAGE, which may exhibit a higher affinity to AGE ligands, resulting in a higher susceptibility to diabetic complications." (PMID 24098713, 2013). "However, an exogenous supply of insulin often leads to severe hypoglycemia-related complications." (PMID 22611393, 2012). "The main advantage of using ICV 2DG compared with insulin-induced hypoglycemia is that the 2DG effects are acutely localized to the brain so that one can study signalling in the hypothalamus in the absence of other potentially confounding systemic effects that could modify the effects in the brain." (PMID 22590531, 2012). "In addition, any insulin infusion sliding scale used to lower the blood glucose level may induce hypoglycaemia, which can lead to devastating effects, such as irreversible neurologic deficit." (PMID 24764523, 2012). "Therefore, persistent suppression of glucagon secretion by exogenous insulin impairs the insulin-glucagon fine-tuning system that predominantly maintains glucose homeostasis, and may result in iatrogenic hypoglycemia." (PMID 23316165, 2012). "The i.p. infusion route has several desirable characteristics: reproducibility of insulin absorption, quick time to peak and return to baseline of insulin action, near-physiological peripheral insulin levels, and restoration of glucagon response to hypoglycemia and exercise." (PMID 24278682, 2012).
Hypoglycemia (continued). "Also, the insulin release rate from these microparticles is dependent on the glucose concentration, thereby making this platform potentially useful in avoiding hyperinsulinemia and corresponding hypoglycemia." (PMID 22272238, 2012). "Therefore, it was reasonable to suggest that the insulin sensitivity, hypoglycemia, and hypolipidemia profile of EEM might be connected to the existence of the phytocompounds, especially the trigonelline." (PMID 22474494, 2012). "Physician dissatisfaction with insulin treatment overall and with glucose control was in the same range as patients, but more physicians (25–45%) were dissatisfied with several other aspects of insulin treatment, including regimen simplicity, hypoglycaemia and injection timing and frequency." (PMID 22313123, 2012). "To test our hypothesis we used an animal model of insulin-induced acute hypoglycemia." (PMID 22998689, 2012). "This strategy could lead to prevention of hypoglycemia in insulin-treated diabetics." (PMID 22969729, 2012). "A key question is also whether it is possible to prevent hypoglycemia in insulin-treated diabetics." (PMID 22969729, 2012). "When episodes of severe hypoglycaemia and nocturnal hypoglycaemia were separately analysed, insulin detemir, but not insulin glargine, was associated with a reduced risk compared to human NPH insulin (OR 0.73 (0.60 - 0.89), p = 0.002 and OR 0.69 (0.55 - 0.86), p = 0.001; respectively)." (PMID 22727048, 2012). "We then hypothesized that if exogenous mealtime insulin was provided with a subcutaneous rapid-acting insulin analog, the postprandial elevation in BG could be attenuated or eliminated, and the subsequent episode of hypoglycemia at 3-4 hours after meal could be prevented." (PMID 22937294, 2012). "Despite this, the majority of recipients benefit from reduced overall insulin requirements; improved C-peptide secretion and HbA1C levels; decreased development of microvascular complications; and fewer complications related to episodes of hypoglycemia after 5-year followup." (PMID 22028949, 2011). "Fear of hypoglycemia by patients and caregivers may adversely affect patients' quality of life and psychological well-being, and may result in 'over-compensatory' behaviors such as overeating or taking less insulin." (PMID 22071283, 2011). "The patients must have tried several insulin treatment regimes, received close follow-ups’ by a diabetologist and despite this continue to have difficulties keeping their blood glucose levels stable, experience hypoglycemic episodes repeatedly and fully or partly lost the hypoglycemia awareness." (PMID 25013604, 2011). "In univariate analyses adjusted for gender, minutes spent in hypoglycemia were significantly correlated with age (r = 0.26; P = 0.01), waist circumference (r = 0.33; P = 0.003), 2-h post-load plasma glucose (r = 0.58; P<0.0001), and 2-h post-load insulin (r = 0.27; P = 0.02)." (PMID 22164268, 2011). "The type of antihyperglycaemic therapy used may influence the risk of hypoglycaemia during a fast, with a higher rate of hypoglycaemia expected with oral agents that enhance insulin secretion in a non-glucose-dependent manner." (PMID 21951832, 2011). "Treatment intensification with incretin-based therapies is appealing given that they provide good glycaemic control with a low risk of hypoglycaemia, because of the glucose-dependent stimulation of insulin secretion and inhibition of glucagon release, and do not produce weight gain." (PMID 21355967, 2011). "However, studies showed that the effect of beta-agonists and insulin together is additive in lowering potassium level, superior to using each of them alone, and may prevent insulin-induced hypoglycemia." (PMID 23882341, 2011). "Indeed, insulin levels should be undetectable at the time of hypoglycemia." (PMID 21967988, 2011).
Hypoglycemia (continued). "- Munchhausen syndrome and Munchhausen by proxy syndrome by insulin injection (high plasma insulin, low c-peptide at the time of hypoglycemia) or by sulfonylurea administration (high insulinemia, high c-peptide and presence of sulfonylurea in plasma and urine at the time of hypoglycemia)." (PMID 21967988, 2011). "Characteristic hypoglycemia, hypotriglyceridemia, hypocholesterolemia, lower body mass, and fat as well as pronounced insulin-sensitivity of RLIP76−/− mice suggested to us the possibility that elevation of RLIP76 in response to stress could itself elicit metabolic syndrome (MSy)." (PMID 21931813, 2011). "Moreover, intensive insulin therapy does not improve outcome of patients with ischaemic or traumatic brain injury and significantly increases the risk of hypoglycaemia which, by itself, can induce neurocognitive dysfunction." (PMID 20374626, 2010). "In the current clinical environment, insulin delivery technology (insulin formulation and pump designs) is well developed, however glucose sensors for continuous in vivo monitoring remain problematic, especially with regards to the kinetic response in the hypoglycemia region." (PMID 22163627, 2010). "Furthermore, portal vein glucose sensors sense slowly developing insulin-induced hypoglycaemia, and during the rapid glucose decline, the critical locus for hypoglycaemic detection shifts away from the portal-mesenteric vein to another central loci (e.g., presumably to the VMH)." (PMID 19442093, 2009). "Furthermore, treatment with insulin in this group is frequently complicated by hypoglycaemia." (PMID 19439067, 2009). "However, since sucralose increases insulin secretion in a dose-dependent manner, high dose of the compound may aggravate hypoglycemia." (PMID 19352508, 2009). "Additional factors predisposing to hypoglycemia have been identified that are more likely to be modifiable including adjustments to nutritional support without concomitant adjustment to insulin administration, use of vasoactive medications, and use of continuous renal replacement therapy." (PMID 19534781, 2009). "However, it is well known that LAIA shows a flat profile of plasma insulin levels and no pronounced peak of activity, both of which are characteristics associated with a lower relative risk of hypoglycemia, especially at night." (PMID 21274293, 2009). "However hyperinsulinemia may result into hypoglycemia which is detrimental to brain function and to prevent this, peripheral insulin resistance develops as a compensatory adaptation." (PMID 17437648, 2007). "Optimising fasting blood glucose (FBG) with premixed insulin may, therefore, increase the risk of hypoglycaemia and may not provide sufficient flexibility for patients to achieve optimal glycaemic control." (PMID 17997807, 2007). "Hence, in the present study, the possible effect of insulin with or without associated hypoglycaemia on small intestinal transit in normal mice was examined." (PMID 16448577, 2006). "It is important to underline that this study was conducted prior to the era of tight glucose control, but due to the risk of hypoglycaemia, insulin treatment is still not standard during the early resuscitation period in our unit although we do use an aggressive glucose control protocol thereafter." (PMID 17166287, 2006). "The initial high‐dose insulin infusion, based on a standard DKA protocol, led to rapid ketone clearance but also hypoglycemia." (PMID 41509085, 2026). "Additionally, patients with T2D using non-intensive insulin regimens or sulfonylureas may be at risk of hypoglycemia, especially if SMBG is not performed adequately." (PMID 41601933, 2026). "The literature mentions that tirzepatide can cause mild to moderate hypoglycaemia as an adverse effect; however, the overall pattern suggests that it has a low risk of significant symptomatic hypoglycaemia, especially if not combined with insulin or sulfonylureas." (PMID 41566974, 2026).